IL33 (interleukin 33)
Diseases named in the same sentence as IL33 in open-access papers (continued):
Sharing a sentence is not in itself a finding about the gene and the disease.
tumor (continued). "In addition, IL-33 treatment is indicated to upregulate PD-1 expression in a fraction of tumor ILC2s; thus, a combination treatment of recombinant IL-33 and anti-PD-1 may maximally activate and enrich ILC2s in PC and enhance tumor control." (PMID 35409105, 2022). "IL-33 may promote CRC tumour invasion and metastasis through desmoplastic reactions." (PMID 36263033, 2022). "Furthermore, IL-33-mediated recruitment of M2-like TAMs promoted tumor metastasis." (PMID 34209038, 2021). "Additionally, the high tumor tissue levels of IL-33 correlated with a favorable prognosis in patients with either iCCA or pCCA while granulocyte colony-stimulating factor (G-CSF) were suggested as a prognostic biomarker to predict tumor recurrence after resection." (PMID 34203269, 2021). "IL33 may also enhance a type 2 microenvironment once the tumor is established." (PMID 34235145, 2021). "Finally, in vivo, we confirmed that IL‐33 promotes tumour progression." (PMID 33305406, 2021). "Moreover, exogenous IL-33 mimicked the effects observed in case of injury and cooperated with KRAS mutation to activate the neoplasia-specific and BRD4-dependent gene expression program, associated with an accelerated appearance of pancreatic intraepithelial neoplasia." (PMID 34023857, 2021). "Apart from triggering the IL-33/ST2 signaling to augment cancer immunotherapy, a number of studies showed the blockade of IL-33, ST2, or both resulted in growth inhibition of tumors in association with reduced accumulation of ST2+ tumor-promoting cells, such as Treg, TAM, and IL17RB+ILC2." (PMID 34209038, 2021). "In addition, IL-33 and ST2 levels have been found to be higher in breast tissues with cancer, as compared to healthy breast tissues, which may suggest a role for the IL-33/ST2 axis in tumor progression." (PMID 33946554, 2021). "Based on the IL‐33 levels in this study and their association with the enhanced infiltration of local M2 macrophage in ESCC tumours, we investigated whether IL‐33 could induce the M0‐to‐M2 macrophage differentiation by treating the M‐CSF–induced PBMC‐derived macrophages with IL‐33." (PMID 33305406, 2021). "However, recent studies demonstrated that IL-33 can induce an anti-tumor response via Th1 activity." (PMID 34209038, 2021). "Besides the direct delivery of IL-33, an interesting study reported endogenous IL-33 was released from stromal cells targeted by a lymphocytic choriomeningitis virus (LCMV)-based replication-competent vector delivering tumor-specific antigen to DC for efficient priming." (PMID 34209038, 2021). "Interestingly, we showed the inducible expression of immune checkpoint molecule PD-1 on effector CD8+ T cells and elevated levels of PD-L1 on tumor cells by IL-33 treatment, thereby providing a strong rationale for combination therapy of IL-33 and immune checkpoint blockade (ICB)." (PMID 34209038, 2021). "Indeed the use of intratumoral injections of IL-33 promotes antitumor activity of ILC2s either through IL-5 and GM-CSF, which control tumor growth, through the recruitment of eosinophils or through the production of CXCR2 ligands with lytic activity on CXCR2+ tumor cells." (PMID 33233582, 2020). "Also here, treatment with IL-33 reduced tumor growth, as evaluated by tumor number and tumor area." (PMID 32923137, 2020). "However, tumour-infiltrating effector-memory CD8+ T cells in surgically resected tissues producing IL-33 could prolong the survival of HCC patients." (PMID 33308251, 2020). "Thus, increased S100A9 was found at the RNA and protein levels after IL-33 treatment, which may provide a pre-metastatic niche that could lead to tumour occurrence." (PMID 33308251, 2020). "Here, we asked whether eosinophils are involved in the effects of IL-33 on tumor growth in CRC." (PMID 32923137, 2020). "In LSCC, IL-33 may increase the extent of malignancy of tumor cells and act as a pro-tumor factor." (PMID 33634017, 2020).
tumor (continued). "Therefore, the balance between different proteases as well as the nature of tumor cell death (necrotic vs apoptotic) may dictate the activity of IL-33 within the TME." (PMID 33329534, 2020). "Moreover, in the absence of reprogramming of the tumor environment by nuclear IL-33, the innate immune cells may remain in a phenotype that is tumor suppressive and thereby maintain control of tumor growth." (PMID 33447733, 2020). "IL-33 from the stroma could be a pro-tumor factor, as it is in the setting of LSCC." (PMID 33634017, 2020). "IL-33 may be a key tumour promoter that promotes the proliferation and tumourigenicity of HCC." (PMID 33308251, 2020). "In addition, IL-33 prevented chemotherapy-induced tumor apoptosis." (PMID 32003751, 2020). "Notably, both antitumor TH1 and pro-tumor TH2 cells were downregulated in the high IL-33 group." (PMID 33634017, 2020). "Moreover, IL-33 prevented temozolomide induced tumor apoptosis." (PMID 32003751, 2020). "However, the manner in which IL-33 expression regulates tumour epithelial and stromal cells remains unclear." (PMID 33308251, 2020). "However, IL-33-activated tumor-infiltrating ILC2s expressed PD-1." (PMID 32695313, 2020). "However, both pro-tumoral and anti-tumoral functions have been reported, and IL-33 may differently influence tumor immunity depending on the tumor type, relevant immune cell targets, and microenvironmental factors." (PMID 31500217, 2019). "Mast cell activation by IL-33 may occur in a variety of tumor types." (PMID 31500217, 2019). "Interestingly, tumor IL-33 levels were increased in those patients with LN metastasis." (PMID 31281317, 2019). "From this perspective, using a cohort of Chilean patients, we analyzed the association of IL-33/ST2 content and distribution with CRC progression and clinical/histopathological features (TNM staging, desmoplasia, tumor localization, among others) in tumor and healthy tissue." (PMID 31281317, 2019). "Eosinophils remained elevated in the lungs after primary tumor resection, which may be related to the high levels of IL-33 release we have previously observed in the lungs of 4T1 tumor-bearing mice since IL-33 is known to activate eosinophils and induce eosinophilic airway inflammation." (PMID 31488209, 2019). "Furthermore, in oral squamous cell carcinoma, LncRNA-CAF could elevate the expression of cytokine IL-33 to promote the activation of CAFs, leading to proliferation of tumor cells." (PMID 31448238, 2019). "Thus, IL-33 signaling provides a target to restrict the tumor promoting activities of the myeloid compartment and may ultimately enable rational combination therapies to alleviate the activity by which myeloid cells limit the antitumor immune response." (PMID 31227713, 2019). "In addition, the frequency of CD4+ FOXP3+ Tregs, the proportion of ST2+ CD4+ FOXP3+ Tregs, and IL-33 protein expression in the colon all positively correlated with tumor scores (i.e. the sum of the relative size of all tumors in a given mouse), irrespective of the genetic background." (PMID 31165767, 2019). "Thus, it is likely that eosinophils may operate through a similar mechanism and that IL-33 may facilitate both synapse formation and granule convergence, leading to targeted tumor cell killing." (PMID 31717819, 2019). "Furthermore, the study of the nuclear IL-33 action will be useful to evaluate the possible interactions with tumor-related transcription factors, and the modulation of nuclear IL-33 expression could represent a possible therapeutic approach." (PMID 31652497, 2019). "Moreover, these FOXP3+ lymphocytes were located in the vicinity of IL-33-expressing tumor cells." (PMID 31165767, 2019). "However,whether IL-33 induced expression if ST2L in tumor-infiltrating Tregs or IL-33 induced therecruitment of ST2L+Tregs into the tumor bed where they contribute to CRCdevelopment need further study." (PMID 29950152, 2018).
tumor (continued). "In this respect, the tumor histotype may crucially determine the amount of IL-33 expressed." (PMID 30483263, 2018). "Thus, the IL-33/ST2 interaction is associated with decreased frequencies of NK cells in the tumor environment and decreased cytotoxic activity, indicating that IL33/ST2 plays a suppressive role in NK cell functions during tumor development." (PMID 30112116, 2018). "Thus, targeting FAK/IL-33-mediated signals may enhance the ability of the patient’s immune system to find and eliminate tumor cells." (PMID 30205617, 2018). "Thus, one of the possible mechanisms for IL-33 in promoting human cancer progression is through increased accumulation of immunosuppressive cells within the tumor microenvironment and by diminishing innate anti-tumor immunity." (PMID 30547011, 2018). "Thus, elevated epithelial IL-33 signaling increased tumor development in the ApcMin/+ mice." (PMID 30205617, 2018). "Thus the expression of IL-33 by the tumours diminished the accumulation of immune suppressive cells and promoted elevated numbers of infiltrating CD68+ tumour-associated macrophages and neutrophils in the metastatic IL-33-expressing tumours compared to unmodified metastatic tumour." (PMID 29440650, 2018). "In addition, reduced lung volume due to surgical removal of the tumor may also decrease IL-33 levels by diminishing bronchial and vascular endothelial volumes." (PMID 30205617, 2018). "As a tumor biomarker, IL-33 could be versatile serving as a therapeutic target in patients." (PMID 30619376, 2018). "IL-33 may regulate tumor growth by affecting stromal cells or immune responses." (PMID 30119635, 2018). "Amongst these cytokines, Interleukin-33 (IL-33), a member of the IL-1 superfamily of cytokines, is well-known now to have an important role in innate and adaptive immunity through its contribution to tissue homeostasis and responses to stress such as tumor development." (PMID 30416507, 2018). "In addition, the level of IL-33 protein was inversely correlated with tumor grade and size." (PMID 29499051, 2018). "Our data support the model that IL-33 dependent tumour-infiltrating ILC2s are mobilized from the lungs and other tissues through chemoattraction to enter tumours, and subsequently mediate tumour immune-surveillance by cooperating with dendritic cells to promote adaptive cytolytic T cell responses." (PMID 29440650, 2018). "Mast cell activation by IL-33 may occur in a number of tumor types." (PMID 30483263, 2018). "However, other studies report that IL-33 promotes tumor growth." (PMID 28710436, 2017). "Therefore, diminished Treg cells in tumor tissues by IL-33 blockade could contribute to limited NSCLC growth." (PMID 28978138, 2017). "In addition to immune cells, we also find that IL-33 may act on epithelial cells to promote tumor growth." (PMID 28710436, 2017). "Thus, although the role of the IL-33/ST2L axis in regulating tumour progression is controversial, understanding its regulation may provide us with valuable information for controlling the malignant behaviour of CRC." (PMID 27882929, 2016). "We could detect both pro-IL-33 and mature IL-33 in tumour lysates." (PMID 27882929, 2016). "Therefore, IL-33 may promote both Th1 and Th2 responses in the complicated tumour microenvironment, wherein various pro-inflammatory cytokines are abundant." (PMID 27882929, 2016). "Prior to testing this possibility, we examined whether IL-33 was present in tumour tissues." (PMID 27882929, 2016). "Reduced CTCs also corresponded to increased percentages of CD8+ cytotoxic T ccells found in both the tumour and in local lymph nodes, suggesting that IL-33-induced changes may provide favorable conditions for the immune system to reduce metastatic spread, possibly by means of CD8+ T cells." (PMID 27619158, 2016). "Consequently, IL-33-accelerated tumour growth rates are also coupled to increased metastasis." (PMID 27150562, 2016).
tumor (continued). "Therefore, IL-33 released from tumours may activate the NF-κB signalling pathways in tumour-infiltrating inflammatory cells, which in turn may be attenuated by sST2." (PMID 27882929, 2016). "Finally, a very recent manuscript describes the role of IL-33 on tumor immunology." (PMID 26082774, 2015). "However, in high grade tumor tissue, the expression of IL-33 is decreased compared to low grade tumor tissues, indicating that IL-33 may be more important in HER2-over-expressing tumors, and other cytokines may be involved in this crosstalk of regulation." (PMID 24778632, 2014). "IL-33 may have a significant role in tumor angiogenesis and immunosurveillence." (PMID 24959294, 2014). "As IL-33 may play an important role in immunosuppression of cancer for subsequent tumor progression and metastasis, and auto-immune diseases are usually hereditary, patients with a family history may be more likely to trigger or promote the process of immunosuppression." (PMID 24778632, 2014). "IL-33 expression in adjacent tissues also tends to be higher compared to normal tissues, suggesting that adjacent non-cancerous tissues may be similarly relevant to cancers in terms of anti-tumor immunity." (PMID 24778632, 2014). "From this point of view, IL-33 may represent one of the effective weapons tumor cells utilize in order to create an ideal environment to obtain, and maintain, optimal growth conditions, further supporting the role of the IL-33/ST2 axis in tumor formation and the progression of cancer." (PMID 23847622, 2013). "Therefore, IL-33 may be an important mediator in tumor escape from immune control and in tumor angiogenesis and thus warrants further investigation." (PMID 21871091, 2011). "We then asked whether IL-33 is expressed in blood vessels from human tumor tissues." (PMID 18836528, 2008). "Co-electroporation of IL-33 mutein and IL-12 mRNA in PMEL-1 T cells led to synergistic increases in IFN-γ production, cytotoxicity, and long-term memory, resulting in superior tumor control and protection upon rechallenge." (PMID 41608588, 2026). "Herein, we show that IL-33/ST2 stimulates the NHEJ pathway and resistance to DNA damage-inducing chemotherapeutic drugs in tumor cells, providing a direct link between abnormal DDR and the IL-33-mediated network." (PMID 40216748, 2025). "The attraction of MCs to a tumor requires the action of different chemokines produced by the tumor cells such as the stem cell factor (SCF), CXCL2, CCL2, CCL5, CCL11, CXCL12, CCL15, IL-3, and IL-33." (PMID 41465542, 2025). "For instance, CAFs secrete factors like IL-6, IL-33, and TGF-β, which activate signaling pathways in tumor cells, promoting tumor progression." (PMID 41031085, 2025). "For example, CSCs evade immune surveillance by inducing macrophage polarisation towards the M2 type through the secretion of IL‐33 and TGF‐β or by inhibiting anti‐tumour immune responses by binding PD‐L1 to T‐cell surface receptors." (PMID 40665579, 2025). "Targeting interleukin (IL)-33, IL-13, and ILC2 activation suppressed metaplasia and tumor progression in APP mice." (PMID 40761291, 2025). "Our analysis of differential expression indicated that ANO6 and IL33 were markedly downregulated in cancerous tissues relative to normal ones, whereas SIAH2 showed elevated expression in tumor samples." (PMID 39911848, 2025). "Most importantly, DAC and IL-33 synergistically enhanced the expression of PD-1 within the TME and the percentages of PD-1 expressing tumor-infiltrating CD8 and CD4 T cells, resulting in improved in vivo response to PD-1 blockade." (PMID 40317004, 2025). "New therapeutic approaches, which are under preclinical evaluation, include the use of antibodies that neutralize IL-33 or ST2, especially in tumours with intensive accumulation of Treg cells or fibrous stroma." (PMID 41284319, 2025). "In contrast, the proteins CAMK2A, IL33, IRF9, and TRAF5 were primarily expressed in normal tissues and exhibited reduced expression in tumor tissues." (PMID 40893939, 2025).
tumor (continued). "Once secreted, IL-33 interacts with immune cells expressing ST2, initiating downstream signalling cascades in the same cells that can ultimately lead to tumour suppression or promotion, depending on the prevailing immune context and local microenvironment." (PMID 41284319, 2025). "TPCs secrete factors like IL-33, CXCL12, and CXCL14, which recruit immune cells to promote a pro-tumor environment." (PMID 40784879, 2025). "Conversely, blocking the IL-33/ST2 pathway has been shown to reprogram the TME, leading to increased infiltration of cytotoxic T lymphocytes and enhanced anti-tumour responses." (PMID 41284319, 2025). "Intratumor fungi facilitate the secretion of IL-33 from PDAC mice cells and accelerate PDAC mice tumor growth." (PMID 40641932, 2025). "Another finding reported in this study is the requirement of IL-33/ST2 axis for immune recruitment to the TME and for in vivo anti-tumor efficacy of DAC." (PMID 40317004, 2025). "In human PCa, IL-33 and MHC-I/HLA genes are co-ordinately downregulated during metastatic reprogramming, indicating a potential role for IL-33 in tumour progression and immune evasion." (PMID 40607441, 2025). "In PDAC, an IL‐33:ILC2 axis appears to orchestrate superior CD8 T cell responses, potentially via improved recruitment of CD103+ DCs into the tumour." (PMID 40899118, 2025). "Conversely, in tumours with pre-existing effector infiltration (high TILs, active IFN-γ signalling), transient IL-33 release can facilitate CTLs and NKs cytotoxicity." (PMID 41284319, 2025). "Mice deficient for the IL-33 receptor ST2 (ST2−/− mice) were employed to address the role of endogenous IL-33 signaling in DAC therapeutic response and tumor-immune crosstalk." (PMID 40317004, 2025). "By screening differentially expressed cytokines in LX2 cells activated by various tumor cells, we found that the expression of CSF2, IL33, COX2, and IL17A was upregulated." (PMID 41214328, 2025). "According to Alam and co-authors, intratumor fungi facilitate the secretion of IL-33 from PDAC cells and accelerate PDAC tumor growth." (PMID 40641932, 2025). "The addition of the mTOR inhibitor rapamycin reduced IL33-induced LD formation and DGAT1/2 and PPARG expression, as well as the survival ability, proliferation ability, and ability to promote tumor cell proliferation of teHDNs." (PMID 41214328, 2025). "However, we emphasize that the intense IL-33 nuclear expression patterns were completely lost in the intratumoral areas, as well as in lymph nodes with occult metastasis, suggesting that assessing nuclear IL-33 expression can contribute to ruling out tumor cell invasion." (PMID 41374934, 2025). "Emerging studies have proved that the IL-33/ST2 axis is involved in diverse immune responses, restoring normal tissue homeostasis via promotion of wound healing and repair, and is essential in tumor progression." (PMID 39925809, 2025). "Recent experimental findings suggest that simultaneous manipulation of the IL-33/ST2 and PD-1/PD-L1 signalling axes represents a potent strategy for enhancing antitumor immunity and controlling tumour progression." (PMID 41284319, 2025). "Higher TNF-α/IL-33 and TNF-α/IL-4 ratios in responders suggest the predominance of proinflammatory potent stimulator TNF-α of anti-tumor immune response in NET patients who responded better to therapy and diminished immunosuppressive effect of IL-33 and IL-4." (PMID 40943444, 2025). "IL‐33 is expressed mainly in endothelial cells in clinical samples, while its receptor, ST2, is expressed mainly in tumor cells." (PMID 40860436, 2025). "Our data thus show that the host brain responds to tumor growth by upregulating IL-33, which can be found as complexes with its receptor, ST2, both close to the tumor, and far from the tumor site, suggestive of an inflammatory response." (PMID 39931535, 2025). "The IL-33/ST2 axis significantly configures the tumor microenvironment and tumor aggressiveness in HNSCC." (PMID 40196136, 2025).